TNFRSF25 (TNF receptor superfamily member 25)
Diseases named in the same sentence as TNFRSF25 in open-access papers (continued):
Sharing a sentence is not in itself a finding about the gene and the disease.
tumor (40 papers, 2008 to 2025). "Growth factor-related genes are also associated with tumor metastasis, among which LTα, TNFRSF12α, TNFRSF25, TNFRSF4, and IRF9 can mediate HNSCC tumorigenesis and metastasis through the NF-κB signaling pathway." (PMID 33330624, 2020). "Thus, TNFRSF25 may be a key immune checkpoint molecule mediating the effect of BACE1-AS on tumor progression, and further study on the association between the two may help to develop new therapeutic targets." (PMID 34926701, 2021). "Stimulating immune receptors’ TNFRSF25 can enhance the eradication of tumor cells by T cells, and CD40LG activates immune cells and enhances inflammatory responses." (PMID 39062659, 2024). "In terms of immune checkpoints, the expressions of CTLA4, CD276, CD47 and TNFRSF25 were significantly higher in “stiff tumor”." (PMID 37179366, 2023). "Therefore, it can be speculated that CD27, PDCD1, TMIGD2 and TNFRSF25 may participate in tumour immunity by regulating IMCPs." (PMID 37849388, 2023). "However, the binding of TNFSF15 to its receptor, TNFRSF25, amplifies the expression of IL-4, IL-6, GM-CSF, and IL-1758,59, which may explain the overactivity of these tumour-promoting cytokines in our network." (PMID 29062084, 2017). "An analysis of these immune checkpoints in tumor and normal samples revealed significant differences in the expression of CD200, CD274, TIGIT, TNFRSF25, and TNFSF15 between the two groups (P < 0.05)." (PMID 40666524, 2025). "The stiff subtype exhibited significantly increased tumor mutual burden and T cell follicle helper cell levels compared with the soft subtype, along with the expression of CTLA4, CD276, CD47, and TNFRSF25." (PMID 40277910, 2025). "Among immunostimulators, CD276, PVR, TNFRSF14, TNFRSF25 and TNFSF9 were also negatively correlated with LAMP3 expression in some tumours." (PMID 38146591, 2024). "Therefore, CD27, PDCD1, TMIGD2 and TNFRSF25 may participate in tumour immunity by regulating IMCPs." (PMID 37849388, 2023). "Members of the TNF receptor superfamily (TNFRSF) are the key co-stimulators of T cells, and TNFRSF25 can promote CD8+ T cell responses and anti-tumor immunity." (PMID 35280985, 2022). "Of these, eight showed highly significant hypermethylation in tumor tissue (p < 0.0001): GDNF, MTHFR, OPCML, TNFRSF25, TCF21, PAX8, PTPRN2 and PITX2." (PMID 18616821, 2008). "Furthermore, significant differences in the expression of immune checkpoints—specifically CD200, CD274 (PD-L1), TIGIT, TNFRSF25, and TNFSF15—were observed between tumor and normal samples." (PMID 40666524, 2025). "TNFRSF25 agonists can stimulate CD8+T cells and exert anti-tumor effects." (PMID 41001045, 2025). "In addition, we compared significant immune checkpoints between “stiff tumor” and “soft tumor” and observed the expression of CTLA4, CD276 and TNFRSF25 was higher in “stiff tumor”, while the expression of CD47 was higher in “soft tumor”." (PMID 37179366, 2023). "The results showed that m6Ascore was negatively correlated with the expression of TMIGD2, TNFRSF18, TNFRSF25, TNFRSF4, TNFRSF8, and NRP1, indicating that the poor prognosis of high-m6Ascore patients might be due to the tumor immunosuppressive microenvironment." (PMID 36313417, 2022). "However, in non-metastasis conditions, the TNFSF12 ligand from eCAFs/myCAFs increased communications with TNFRSF25, while in metastasis conditions, this ligand increased communication with TNFRSF12A in p-EMT tumor cells." (PMID 35742914, 2022). "TNFRSF25 expression was not significantly difference between tumor tissues and normal tissues in the TCGA dataset." (PMID 34484286, 2021). "Additionally, neo-antigen load correlated with increased expression of the chemokines TNFRSF25, CCR1, and LTBR, which may serve as valuable targets in future tumor immunology studies." (PMID 29487705, 2018). "Indeed, MTHFR, OPCML, TNFRSF25 and TCF21 show highly statistically significant differences (p < 1 × 10-6) between tumor and adjacent non-tumor tissues in our study." (PMID 18616821, 2008).
infection (9 papers, 2009 to 2025). The state of being infected such as from the introduction of a foreign agent such as serum, vaccine, antigenic substance or organism. "Tnfrsf25 showed the biggest fold change among downregulated genes in the RORα-deficient KLRG1+ effector T cells isolated at days 7 and 10 after primary infection." (PMID 40895530, 2025). "An increase in mRNA levels similar to microarray data was confirmed by qRT-PCR at 8 and 24 h post-infection for both GADD34 (2.25 fold increase at 8 h and 2.65 fold increase at 24 h) and TNFRSF25 (2.4 fold increase at 8 h and 3.61 fold increase at 24 h) (data not shown)." (PMID 19146679, 2009).
bone disorder (2 papers, 2016 to 2017). "Moreover, it has been reported that the absence of TNFRSF25 protects from the development of severe bone disorders in experimental antigen-induced arthritis (AIA)." (PMID 28441778, 2017).
TNFRSF25 also shares sentences with these, for which no sentence is quoted: colitis (15 papers); asthma (12); Arthritis (8); Autoimmunity (8); rheumatoid arthritis (8); Crohn disease (6); ovarian carcinoma (6); type 1 diabetes (6); diabetes (5); experimental autoimmune encephalomyelitis (5); inflammation (5); allergic disease (4); breast carcinoma (4); Insulin resistance (4); Obesity (4); pancreatic cancer (4); gastric cancer (3); Hashimoto thyroiditis (3); ileitis (3); infectious disease (3); sarcoidosis (3); systemic lupus erythematosus (3); ulcerative colitis (3); autoimmune thyroid disease (2); bacterial infection (2); fibrosis (2); glioblastoma (2); head and neck squamous cell carcinoma (2); hepatocellular carcinoma (2); liver cancer (2).
A further 68 diseases each share a sentence with TNFRSF25 in 2 papers or fewer.